ENSG00000252473
Gene: Small nucleolar RNA gene on chromosome 2 (39,283,657 to 39,283,791, reverse strand). Ensembl gene ENSG00000252473.
Homologues: Orthologues: mouse Gm24147 (56% identical), mouse Gm24493 (56% identical), mouse Gm26494 (55% identical), rat LOC120095402 (52% identical), rat LOC120097975 (52% identical), mouse Gm25480 (50% identical), mouse Gm25697 (36% identical). Paralogues in human: SNORA67 (58% identical).